WNT1 (Wnt family member 1)
Diseases named in the same sentence as WNT1 in open-access papers (continued):
Sharing a sentence is not in itself a finding about the gene and the disease.
breast cancer (continued). "In contrast to the initial mammary tumor development, cKD-Wnt1 and cKO-Wnt1 tumors showed significantly reduced growth rates relative to Ctrl-Wnt1 tumors." (PMID 32493400, 2020). "The increased sensitivity to ER stress-induced cell death also suggests a potential combinatorial therapeutic strategy of FAK ablation along with ER stress induction to treat Wnt1-driven mammary tumors." (PMID 32493400, 2020). "The first link between WNT signaling and breast cancer was established almost 40 years ago, when Wnt1 was identified as a proto-oncogene capable of driving mammary tumor formation in mice." (PMID 32083079, 2020). "Our study is the first to report that HOTTIP regulates the CSC‐like properties of BCSCs by as a molecular sponge for miR‐148a‐3p to increase WNT1 expression, offering a new target for breast cancer therapy." (PMID 32307830, 2020). "Our previous study showed that miR‐148a inhibited breast cancer migration and invasion by directly targeting WNT1." (PMID 32307830, 2020). "Mice lacking cyclin D1 were also resistant to breast cancers induced by the erbB-2 and ras oncogenes, but were sensitive to breast cancers induced by other oncogenes like c-myc or Wnt-1." (PMID 31884567, 2020). "In summary, we show that FAK plays an important role in the maintenance of tumor cell survival in Wnt1-driven basal-like mammary tumors and can serve as a potential therapeutic target for the treatment of basal-like breast cancer." (PMID 32493400, 2020). "Remarkably, CD24 is a direct target of Wnt1 in breast cancer, while CD47 is an indirect target of Wnt signaling mediated by SNAI1 and ZEB1 in breast cancer." (PMID 33234169, 2020). "To gain further insights into potential mechanisms by which FAK regulates Wnt1-driven mammary tumors, we examined FAK deletion-induced changes in various cellular processes and signaling pathways in an unbiased manner by transcriptomic analysis." (PMID 32493400, 2020). "The WNT1 protein was initially identified as a virus-induced proto-oncogene in mouse mammary tumors." (PMID 32301035, 2020). "Nevertheless, Wnt1/34TKO mice had only a slight acceleration in mammary tumour onset with similar penetrance as WT mice (85 and 87%, respectively) and no gross change in mammary subpopulations or tumour histology." (PMID 30093634, 2019). "Starting from a general executable model of breast cancer, we added Wnt1 as a constant node and overlaid high Myc activity." (PMID 31611367, 2019). "Wnt1 transgenic mice (MMTV-Wnt1) represent a suitable mammary tumour model: the Wnt pathway is constitutively active and sufficient to drive mammary tumorigenesis." (PMID 30093634, 2019). "In breast cancer, Tgif1 expression correlated with a poor prognosis and supported the Wnt1-driven cancer development." (PMID 30902975, 2019). "It has been reported that MYC can activate WNT in breast cancer, and in our work, Wnt1 was significantly dependent on MYC (with p-value of 0.002)." (PMID 31213036, 2019). "Module 3 (4 genes) included regulation of cellular response to stress (BRCA1, CTNNB1, HSP90AA1, and WNT1) and breast cancer (BRCA1, CTNNB1, and WNT1)." (PMID 31608105, 2019). "To determine the impacts of different levels of Myc expression on mammary tumors, we used the well-characterized MMTV-Wnt1-driven [B6SJL-Tg(Wnt1)1Hev/J] mouse model of mammary carcinoma." (PMID 31611367, 2019). "Increased expression of the Cancer Stem Cell (CSC) marker SOX2 in human breast cancer activates Wnt-1 signaling to promote resistance to tamoxifen, the most common therapy for Estrogen Receptor-positive (ER+) breast cancer." (PMID 30558303, 2018).
breast cancer (continued). "MiR-148a inhibits breast cancer migration, invasion and angiogenesis by suppressing WNT-1, MMP-13, ERBB3." (PMID 29743122, 2018). "In this paper, we present an in silico approach to classify and quantify IHC staining of the predominantly cytoplasmic marker, Wnt-1, in breast cancer." (PMID 30558303, 2018). "An early link between Wnt signaling and breast cancer was demonstrated by an MMTV integration into the Wnt1 locus, which resulted in mammary tumors in mice." (PMID 30388742, 2018). "To study adipocyte influences on tumour cell migration, we co-cultured mammary tumour fragments arising from either Wnt1 or Her2 overexpressing cells within ET-SIM cultures." (PMID 30139956, 2018). "Here, we evaluate different methods to separate Diaminobenzidine (DAB) from Hematoxylin and Eosin (H&E) staining for Wnt-1, a potential cytoplasmic breast cancer biomarker." (PMID 30558303, 2018). "Stephen Hursting and colleagues from the University of North Carolina at Chapel Hill, USA, established metastatic mouse TNBC cells driven by Wnt-1, a signaling protein that’s highly active in this aggressive subtype of breast cancer." (PMID 28748213, 2017). "Recently, it has been reported that miRNA-148a down-regulated Wnt1 expression by directly targeting its 3’UTR in breast cancer and mesenchymal stem cells." (PMID 28199399, 2017). "Similarly, WNT1 overexpression induced by a proviral insertion at the Wnt1 locus induces spontaneous mammary hyperplasia and tumours in mice, and Wnt1 transgenic mice similarly develop mammary tumours, suggesting a causative role for WNT1 in breast cancer tumorigenesis." (PMID 29137258, 2017). "In this vein, Liu and coworkers found drastic differences in the vascular content of mammary tumors induced by overexpression of Wnt1 compared with mammary tumors induced by overexpression of Her2." (PMID 29240722, 2017). "Wnt signaling plays a critical role in embryonic development 19, which is well established, while its role in cancer was first described three decades ago 20 in Wnt1 transgenic mouse models of mammary cancer." (PMID 27139420, 2016). "Work by Provenzano and colleagues demonstrated that in Wnt-1 and PyMT-induced mouse mammary tumors, collagen fibers organize progressively around the tumor islets." (PMID 26909794, 2016). "For example, although Rspo2 and Wnt1 are both found as common integration sites in the MMTV-induced mouse mammary tumor model, Rspo2- and Wnt1-transformed mammary epithelial cells behave differently in vivo." (PMID 27338477, 2016). "Wnt-1 is detected predominantly in invasive breast carcinomas and the expression of Wnt-1 is required for epithelial-mesenchymal transition of breast cancer cells." (PMID 27036017, 2016). "Consistent with this, our results show that miR-148a suppresses breast cancer metastasis possibly through down-regulation of WNT1." (PMID 26967387, 2016). "Overall, greater than sixty WNT1/FGF3 targets (related to mitochondria, glycolysis, the EMT, and protein synthesis) that we identified in MCF7-WNT1/FGF3 cells were also transcriptionally elevated in human breast cancer cells in vivo." (PMID 26421711, 2015). "We previously show that leptin induces canonical activation of Wnt1 signaling through β-catenin-dependent mechanisms in breast cancer cells." (PMID 26036628, 2015). "In this study, a transplantable mouse model for Wnt1/iFGFR1-driven breast cancer was employed to demonstrate changes in the stromal microenvironment and EGFR signaling occurring during tumor dormancy and recurrence." (PMID 26581390, 2015). "HNK inhibited migration of breast cancer cells which was additionally reduced with ICG co-treatment while Wnt1 co-treatment interfered with HNK-mediated inhibition of migration." (PMID 26036628, 2015).
breast cancer (continued). "To elucidate the mechanisms driving tumor recurrence, we employed a transplantable Wnt1/inducible fibroblast growth factor receptor (FGFR) 1 mouse mammary tumor model and utilized an FGFR specific inhibitor, BGJ398, to study the recurrence after treatment." (PMID 26581390, 2015). "MMTV initiates mammary tumorigenesis in mice by promoter insertion adjacent to two main integration sites, namely Int-1 (Wnt1) and Int-2 (Fgf3), which ultimately activates Wnt/β-catenin signaling, driving the propagation of mammary cancer stem cells (CSCs)." (PMID 26421711, 2015). "Owing to its oncogenic function, Wnt1 treatment resulted in increased growth of breast cancer cells and Wnt1 treatment abrogated HNK-mediated growth inhibition." (PMID 26036628, 2015). "We investigated the roles of Wnt1 in the invasion and migration of breast cancer cells by transwell migration assay." (PMID 26202299, 2015). "In contrast, activation of the Wnt1 proto-oncogene results in the formation of ER+ ductal-like breast cancers, presumably by Wnt/ß-catenin independent mechanisms." (PMID 25149534, 2014). "In contrast, an increase in the PTEN expression level reduces the Wnt-1-induced onset of mammary tumors, which indicates that the PI3K/AKT pathway is a good target candidate for treating mammary cancer." (PMID 25295225, 2014). "Nanog overexpression along with Wnt1 in mouse mammary gland resulted in mammary tumorigenesis and metastasis and promoted the migration and invasion of breast cancer cells." (PMID 25348805, 2014). "In the three decades since the discovery of the Wnt1 proto-oncogene in virus-induced mouse mammary tumours, our understanding of the signalling pathways that are regulated by the Wnt proteins has progressively expanded." (PMID 25208913, 2014). "It was suggested that activation of the Wnt1 proto-oncogene targets a common luminal progenitor, which results in ER+ mammary cancers." (PMID 25149534, 2014). "It was found that MMTV insertions near the Wnt1 gene promoted mammary tumor development via activation of Wnt1, the founding member of the Wnt signaling pathway." (PMID 23690930, 2013). "We chose Erbb2 and Wnt1 as the initiating oncogenes, because their gene products activate two distinct pathways that are frequently altered in human breast cancer." (PMID 24381245, 2013). "The first mammalian Wnt gene, Wnt1, was originally identified as a locus activated by retroviral insertion of mouse mammary tumor virus (MMTV), and transgenic Wnt1 overexpression was subsequently shown to drive mammary tumor formation in mice." (PMID 22457761, 2012). "The observation in Wnt1/Fgf3 bitransgenic mice that mammary tumor development is a stochastic event is consistent with the necessity for collaborating events during mammary tumor progression." (PMID 23131872, 2012).
breast cancer (continued). "Wnt1 has been shown to require mTOR activation during breast cancer cell proliferation, to drive hair follicle proliferation and stem cell modulation, and to promote inflammatory cell survival during oxidant stress." (PMID 22388478, 2012). "In both TP and TBP tumors, we observed squamous metaplasia that was characterized by keratin nests and high expression of Keratin 6, a marker of progenitor cells that is expanded in Wnt-1-induced mammary tumors." (PMID 23173005, 2012). "The prototypic Wnt gene, Wnt1, was originally isolated during analysis of chromosomal insertion sites enriched in murine mammary tumors induced by mouse mammary tumor virus (MMTV)." (PMID 24212796, 2011). "Wnt itself was first identified as an oncogene that is activated by the insertion of the mouse mammary tumor virus; and the mouse mammary tumor virus-Wnt-1 transgenic mouse is a well-established model for studies of the genetic basis of breast cancer." (PMID 20507565, 2010). "Because wnt1 pathway activation is involved in human breast cancer, and RARα has a proven role in breast cancer, the mechanism connecting RARα1 to control of wnt-tumorigenicity is worthy of further study." (PMID 20923554, 2010). "Here, we report novel crosstalk between ILK and Wnt1 oncogenes, resulting in accelerated breast cancer development with molecular characteristics consistent with a more-aggressive phenotype in vivo." (PMID 20565980, 2010). "The extremely high level of Pea3 expression in MMTV/Wnt1 mammary tumors rendered it technically challenging to reliably achieve X-gal staining of tumor samples, due to rapid precipitation of reaction product on the tissue surface." (PMID 20107508, 2010). "In aggregate these data suggest the MMTV/Wnt1 strain as a potentially useful model of basal breast cancer in humans." (PMID 20107508, 2010). "The Wnt1/ILK transgenic model of mammary tumor development shows evidence of expansion of the luminal progenitor cells with a highly active ER-α transcriptional network." (PMID 20565980, 2010). "First, a large percentage of mammary tumors derived from MMTV-infected wild type mice have “hits” at both Wnt1 and Fgf3; it is likely that additional genes are activated in these tumors." (PMID 21274409, 2010). "Among those is FOXA1, which shows an average fourfold increase in expression in double-transgenic mammary tumors compared with Wnt1 tumors with > 95% confidence interval." (PMID 20565980, 2010). "Transactivations of ER-α machinery, as well as the enhancement in nuclear accumulation of β-Catenin also support the observed upregulation of cyclin D1 in Wnt1/ILK double-transgenic mammary tumors." (PMID 20565980, 2010). "To begin investigating the cooperation between ILK and Wnt signaling pathways in mammary tumor formation we needed to determine how overexpression of ILK would affect Wnt1-induced mammary tumor development." (PMID 20565980, 2010). "We have previously identified Pea3 as being extremely highly expressed in mammary tumors from MMTV/Wnt1 transgenic mice." (PMID 20107508, 2010). "Western-blot analysis of β-catenin showed greater than twofold increase in β-catenin expression in Wnt/ILK double-transgenic tumors compared with Wnt1-induced mammary tumors." (PMID 20565980, 2010). "And in another study, breast cancers induced by Wnt-1 overexpressed a series of MMPs, including MMP-2 and MMP-9, except MMP-7, a long held Wnt target gene in intestinal tumors." (PMID 19586554, 2009). "Wnt1-induced mouse mammary tumors share a transcriptional signature with Brca1+/− and carcinogen-induced tumors, and these in turn share components of their basaloid signature with human basaloid tumors." (PMID 19672307, 2009).
breast cancer (continued). "In this study, we determined the anti-cancer effect of Rapamycin in Wnt-1 mouse model of breast cancer and also the effect of Rapamycin treatment on the cellular composition and function of lymphoid organs in vivo." (PMID 18570671, 2008). "We used Wnt-1 transgenic mammary tumor transplantation model that allows generation of virtually unlimited numbers of synchronous transgenic tumors in syngeneic recipients with remarkable stability of the genome." (PMID 18570671, 2008). "In conclusion, Wnt-1 mammary tumor transplanted into syngeneic hosts is a valuable model for studying the effect of immune system on cancer." (PMID 18570671, 2008). "Rapamycin has a direct anti-tumor effect on Wnt-1 breast cancer in vivo that involves inhibition of the mTOR pathway at doses that also suppress host immune responses." (PMID 18570671, 2008). "We examined the effect of Rapamycin on the immune system and growth of MMTV-driven Wnt-1 mammary tumors which were transplanted into irradiated and bone marrow-reconstituted, or naïve mice." (PMID 18570671, 2008). "Taken together, these data demonstrate that, in human breast cancer cells, Wnt1 activates the ERK1/2 pathway in a WNT ligand- and DVL-dependent manner and this is independent of canonical signaling via β-catenin stabilization." (PMID 17897439, 2007). "β-catenin) was analyzed in these breast cancer cell lines and in a control T47D cell line engineered to ectopically express Wnt1." (PMID 17897439, 2007). "It was recently shown that Wnt1 is induced by progesterone receptor (PgR) signaling in T47D breast cancer cells and that it is required for EGFR transactivation by a PgR agonist in an Src- and metalloprotease-dependent manner." (PMID 17897439, 2007). "In ER-positive mammary tumors from Wnt-1 transgenic mice, tamoxifen treatment resulted in significant reduction of ER expression." (PMID 16280035, 2005). "Wnt-1 was originally described as a proto-oncogene in mouse mammary tumor induced by mouse mammary tumor virus." (PMID 15913453, 2005). "The expression levels of WISP-1, in mammary tumours from Wnt-1 transgenic mice, were high in stromal fibroblasts lying within the fibrovascular tumour stroma, but low focally within tumour cells." (PMID 12865923, 2003). "In addition to their gene expression profiles, TSG101-induced mammary cancers and Wnt1-LateEx tumors share several commonalities, such as their mixed composition of cancer cells with luminal and basal epithelial cell characteristics." (PMID 40624726, 2025). "In addition, there were several genes within the luminal gene expression subcluster that discriminated TSG101-overexpressing and late Wnt1-induced mammary cancers from typical luminal tumors that originated in MMTV-neu and MMTV-PyMT mice (right)." (PMID 40624726, 2025). "Furthermore, the upregulation of Wnt1 expression in C57MG mammary tumor-derived cell line results in elevated levels of Connexin43 protein expression." (PMID 38787118, 2024). "Similarly, in a breast cancer context, two subclones with aberrant expression of Wnt1 were necessary for full tumor expansion as one subclone relied on the Wnt1 secreted by the other for growth." (PMID 37492150, 2023). "Interestingly, we observed that WNT1 was also significantly hypermethylated in other breast cancer subtypes (Luminal A, triple negative and HER2+) in comparison with nontumor controls." (PMID 36393855, 2022). "Therefore, we examined the lungs of mice bearing WNT1‐ or RSPO3‐driven mammary tumors to determine distant metastasis potential." (PMID 36106661, 2022). "Repression of Wnt1 by Six3 has been detected in mammary glands as well as breast cancer cells." (PMID 34490256, 2021). "Furthermore, through IHC analysis, we confirmed that the mammary tumors that were generated in the double transgenic MMTV–Prune-1/Wnt1 mice resemble the TNBC subgroup with undetectable levels of both ERs and PgRs, thus confirming these models as GEMM of TNBC." (PMID 33426510, 2021).